GRIN1 (glutamate ionotropic receptor NMDA type subunit 1)
Diseases named in the same sentence as GRIN1 in open-access papers (continued):
Sharing a sentence is not in itself a finding about the gene and the disease.
polymicrogyria (5 papers, 2018 to 2023). A developmental brain abnormality characterized by an excessive amount of small convolutions on the surface of the brain and cognitive dysfunction. "Here, we report the case of a newborn with AMC, polymicrogyria, and infantile-onset epilepsy caused by a novel GRIN1 variant." (PMID 33062288, 2020). "Polymicrogyria-associated GRIN1 mutations cluster in specific protein domains and significantly alter NMDA receptor function." (PMID 29365063, 2018). "Using whole-exome sequencing we found de novo heterozygous missense GRIN1 mutations in 2 of 57 parent-offspring trios with polymicrogyria." (PMID 29365063, 2018). "We simulated models for the nine polymicrogyria-associated GRIN1 mutations and 16 previous GRIN1 mutations." (PMID 29365063, 2018). "Three polymicrogyria-associated GRIN1 mutations (p.Tyr647Cys, Asn650Ile and p.Ala653Gly) were in close proximity to the S2 domain in a region of highly-conserved residues at the extracellular end of M3." (PMID 29365063, 2018). "Apart from known polymicrogyria genes, GRIN1 was the only gene with de novo mutations in more than one patient." (PMID 29365063, 2018). "Two of the polymicrogyria patients (Patients 1 and 2) had de novo missense mutations in GRIN1 [c.2021A>T, p.(Asn674Ile) and c.2381G>A, p.(Arg794Gln)]." (PMID 29365063, 2018). "We observed that polymicrogyria-associated GRIN1 mutations clustered in the S2 or M3 domains, regions that are significantly depleted of variation in control populations." (PMID 29365063, 2018). "In conclusion, we have found de novo GRIN1 missense mutations in patients with extensive bilateral polymicrogyria." (PMID 29365063, 2018). "This strategy led us to identify two likely causal variants in GRIN1 in patients with extensive bilateral polymicrogyria." (PMID 29365063, 2018). "Six polymicrogyria-associated GRIN1 mutations [p.Arg659Trp (two mutations), p.Asn674Ile, p.Asp789Asn (two mutations) and p.Arg794Gln] were located in the S2 domain." (PMID 29365063, 2018). "Using two-electrode and whole-cell voltage-clamp analysis, we showed that the polymicrogyria-associated GRIN1 mutations significantly alter the in vitro activity of the receptor." (PMID 29365063, 2018). "In contrast to the three potential gain-of-function polymicrogyria-associated GRIN1 mutations, most previous GRIN1 mutations caused dominant-negative effects resulting in a significant loss of receptor function." (PMID 29365063, 2018). "The polymicrogyria-associated GRIN1 mutations tended to cluster in the S2 region (part of the ligand-binding domain of GluN1) or the adjacent M3 helix." (PMID 29365063, 2018). "Overall, our results expand the phenotypic spectrum associated with GRIN1 mutations and highlight the important role of N-methyl-d-aspartate receptor signalling in the pathogenesis of polymicrogyria." (PMID 29365063, 2018). "Our results provide evidence for a genotype–phenotype correlation with most polymicrogyria-associated GRIN1 mutations clustering in the S2 or M3 domains, regions of the protein rarely mutated in non-polymicrogyria patients or the normal population." (PMID 29365063, 2018). "However, a simple model of gain-of-function GRIN1 mutations causing polymicrogyria is challenged by the results for p.Asn674Ile." (PMID 29365063, 2018). "We hypothesized that polymicrogyria-associated and previous GRIN1 mutations might have different effects on the structure of GluN1." (PMID 29365063, 2018). "Therefore, having observed two de novo GRIN1 mutations in patients with polymicrogyria, we searched for additional GRIN1 mutations in MCD patients." (PMID 29365063, 2018).
polymicrogyria (continued). "In addition, we showed that polymicrogyria-associated GRIN1 mutations significantly alter in vitro NMDA receptor function." (PMID 29365063, 2018). "In addition, the GluN1 S2 domain has rarely been mutated in non-polymicrogyria GRIN1 patients." (PMID 29365063, 2018). "To investigate whether polymicrogyria-associated GRIN1 mutations influence NMDA receptor function in vitro we undertook site-directed mutagenesis to introduce five of the GRIN1 mutations (p.Tyr647Cys, p.Arg659Trp, p.Asn674Ile, p.Asp789Asn and p.Arg794Gln) into cDNA encoding human GluN1." (PMID 29365063, 2018). "We note that at least two previous GRIN1 patients only had CT brain scans, which cannot reliably detect polymicrogyria." (PMID 29365063, 2018). "The reason why some GRIN1 patients get polymicrogyria is uncertain." (PMID 29365063, 2018). "It is also possible that apparently non-polymicrogyria GRIN1 patients (by MRI) may have subtle structural brain abnormalities that are below the resolution of current scanning technology." (PMID 29365063, 2018). "These regions are rarely mutated in the normal population or in GRIN1 patients without polymicrogyria." (PMID 29365063, 2018). "The MRI features seen in previous GRIN1 patients were non-specific volume loss and generalized cerebral atrophy but not polymicrogyria." (PMID 29365063, 2018). "Analysis of transmembrane helix positions and domain-specific RMSD values revealed no consistent differences between previous and polymicrogyria-associated GRIN1 mutations." (PMID 29365063, 2018). "This raises the possibility that some previous GRIN1 patients may have had unrecognized polymicrogyria." (PMID 29365063, 2018). "None were noted to have polymicrogyria (delayed formation of sulci was observed in one patient with homozygous GRIN1 nonsense mutations)." (PMID 29365063, 2018). "Here, we report a case of arthrogryposis multiplex congenita with polymicrogyria and infantile encephalopathy caused by a heterozygous variant, c.1949A>C, p.(Asn650Thr) of GRIN1, which could result in the disruption of the third transmembrane domain (M3) of GluN1." (PMID 33062288, 2020). "Finally, it remains possible that p.Asn674Ile (and other polymicrogyria-associated GRIN1 mutations) may have additional effects that have not been captured by our electrophysiological analysis." (PMID 29365063, 2018).
developmental and epileptic encephalopathy (4 papers, 2023 to 2025). An epilepsy associated with developmental impairment that may be due to either the underlying etiology or the superimposed epileptic activity, or both.
glioma (4 papers, 2021 to 2025). A benign or malignant brain and spinal cord tumor that arises from glial cells (astrocytes, oligodendrocytes, ependymal cells). "Our results revealed the potential sites and pathways that GRIN1 acts upon and validated the diagnostic and prognostic values of GRIN1 in glioma." (PMID 34840971, 2021). "Based on these results, we showed that the dysregulation of GRIN1 could lead to the occurrence of glioma, and its low expression is strongly associated with poor prognosis of patients with glioma." (PMID 34840971, 2021). "By establishing a protein–protein interaction (PPI) network and using Cytoscape software, we identified GRIN1 as a potential biomarker for glioma." (PMID 34840971, 2021). "Subsequently, we browsed the GEPIA database and verified the expression difference of GRIN1 between the high-grade glioma and low-grade glioma." (PMID 34840971, 2021). "In diseases of the nervous system, GRIN1 has frequently been reported in neurodegenerative diseases, while it has been reported to a lower degree in glioma." (PMID 34840971, 2021). "Another box plot proved that the expression of GRIN1 differed among the high-grade glioma group, low-grade glioma group, and normal tissue, whereas the lower expression of GRIN1 represents higher grades of malignancy." (PMID 34840971, 2021). "To confirm the expression difference of GRIN1 in glioma tissues and normal brain tissues, we conducted IHC." (PMID 34840971, 2021). "Notably, glioma patients exhibiting reduced levels of GRIN1 expression tend to have poorer prognoses than those with higher levels of expression." (PMID 40740189, 2025). "The identification of a high number of immune processes with the CHRM1, CHRM3 and GRIN-1 neurotransmission-related gene signature may suggest that NT-related gliomas possess distinct tumor immune microenvironments." (PMID 35455749, 2022). "We believe that GRIN1 can be applied as a novel treatment target for the treatment of glioma." (PMID 34840971, 2021). "Thus, the specific mechanism of GRIN1 expression in the growth, proliferation, and invasion of glioma is still unclear." (PMID 34840971, 2021). "The function of glutamate ionotropic receptor NMDA type subunit 1 (GRIN1) in neurodegenerative diseases has been widely reported; however, its role in the occurrence of glioma remains less explored." (PMID 34840971, 2021). "Another curve graph illustrated that in low-grade glioma (WHO I-II), patients with high expression of GRIN1 also earned a better prognosis than patients with lower expression of GRIN1 (p = 0.0134)." (PMID 34840971, 2021). "In addition, GRIN1 modulates the progression of some tumors; however, no correlative research regarding its function and mechanism in the occurrence of glioma has been reported." (PMID 34840971, 2021). "To look into the regulation of specific cellular signaling pathways by neurotransmitter-related genes in glioma, we performed a correlation analysis of the TCGA glioma dataset between previously-identified NT1-4 discriminatory genes (CHRM1, CHRM3 and GRIN1) and non-neurotransmission-related genes." (PMID 35455749, 2022).
Huntington disease (4 papers, 2015 to 2017). Huntington disease (HD) is a rare neurodegenerative disorder of the central nervous system characterized by unwanted choreatic movements, behavioral and psychiatric disturbances and dementia. "We also found many differentially expressed genes related to the Huntington disease (HD) pathway in both areas of the MPS II mouse model; among these, Bbc3, Bdnf, Crebbp, Dctn1, Dlg4, Gpx1, Grin1, Grin2b, Itpr1, and Pparg are up-regulated, while Dnaic2, Dnali1, Hap1, and Vdac2 are down-regulated." (PMID 28513549, 2017).
Chorea (3 papers, 2018 to 2021). Chorea (Greek for 'dance') refers to widespread arrhythmic involuntary movements of a forcible, jerky and restless fashion. "Furthermore, a genetic phenocopy of NMDAR-antibody encephalitis with mixed hyperkinetic movement disorders (chorea, dystonia, stereotypies, dystonia, oculogyric crises), seizures, and sleep cycle dysregulation is seen with mutations of GRIN1, the gene encoding the NR1 subunit of the NMDAR." (PMID 29053777, 2018).
endometrial cancer (3 papers, 2022 to 2025). Primary or metastatic malignant neoplasm involving the endometrium (mucous membrane that lines the endometrial cavity). "GRIN1 can act as a key gene in the neuro-related classification of endometrial cancer and is associated with calcium signaling." (PMID 40452916, 2025). "For the first time, our findings reveal that CHRM2 and GRIN1 play significant roles in endometrial cancer and are positively related to endometrial cancer prognosis." (PMID 36212450, 2022). "They found that HTR6 and GRIN1 regulated endometrial carcinoma cell migration and the EMT process." (PMID 40661182, 2025). "Further, CHRM2, GRIN1, L1CAM, and SEMA4F were found to be significantly associated with clinical stage, immune infiltration, immune response, and important signaling pathways in endometrial cancer." (PMID 36212450, 2022).
hepatocellular carcinoma (3 papers, 2022 to 2026). A malignant tumor that arises from hepatocytes. "Notably, gene hubs like Drd1, Gria1‐4, Grin1, Grin2b, Grm5, and GABAα receptor genes were also highly connected, mirroring gene expression patterns observed in liver fibrosis, cirrhosis, and hepatocellular carcinoma (HCC)." (PMID 41508419, 2026). "Compared with the GRIN1 low expression group, the GRIN1 high expression group inhibited the Wnt signaling pathway, signaling pathway regulating pluripotency of stem cells, cell adhesion molecules, hepatocellular carcinoma, and gastric cancer." (PMID 36212450, 2022).
multiple sclerosis (3 papers, 2023 to 2025). A progressive autoimmune disorder affecting the central nervous system resulting in demyelination. "Examples include the genes Mtor, which is a major regulator of axonal growth; Dlg4, which encodes the protein PSD95; Grin1, which encodes a critical subunit of NMDA receptors; the neurofilament light chain gene Nefl, which is being developed as a biomarker in traumatic SCI and multiple sclerosis." (PMID 37653491, 2023).
neuroblastoma (3 papers, 2013 to 2021). Neuroblastoma (NB) is the most common solid, extracranial childhood tumor. "To confirm our phosphoproteomic analysis, we analyzed the expression of Grin1 in rat (B104) and mouse (N2A) neuroblastoma cells and the mouse brain." (PMID 24658276, 2014).
nicotine addiction (3 papers, 2010 to 2023). "This then shifted, where day 4 was enriched for the nicotine addiction KEGG pathway, a pathway associated with nicotine-induced alterations in glutamatergic and GABAergic receptors (e.g., GRIN1 and GABRR2) on GABAergic MSNs." (PMID 35563715, 2022).
breast carcinoma (2 papers, 2018 to 2019). "One study analyzed expression of GRIN1 in 12 different human tumor cell lines and concluded it was present in 9 of them including breast cancer." (PMID 30704472, 2019). "GRIN1 or NMDAR1 (N-Methyl-D-Aspartate Receptor Subunit NR1) was shown to be expressed in breast cancer specimens, but not in normal breast and to be involved in tumor growth, being thus, a potential oncogene." (PMID 29854292, 2018).
glioblastoma (2 papers, 2020 to 2021). The most malignant astrocytic tumor (WHO grade IV). "OPRM1- and GRIN1-specific mRNA could be detected in all three glioblastoma lines." (PMID 32560384, 2020). "To test for tumoricidal effects of methadone in glioblastoma, we first analyzed expression of the μ-opioid receptor (OPRM1) and the NMDA receptor subunit ζ1 (GRIN1) in our human glioblastoma cell lines A172, T98G and U251 by RT-PCR and in part, by western blotting." (PMID 32560384, 2020).
Kleefstra syndrome (2 papers, 2020 to 2022). A genetic disorder characterized by intellectual disability, childhood hypotonia, severe expressive speech delay and a distinctive facial appearance with a spectrum of additional clinical features. "Interestingly however, a recentstudy has demonstrated increased Grin1 expression andNMDA-R hyperactivity in iPSCs derived from Kleefstra syndrome patients." (PMID 32954001, 2020).
Type 2 Diabetes (2 papers, 2025 to 2026). "Furthermore, research has identified new links between the polymorphic loci in the GRIN1 gene (rs6293) and external eating behaviors in individuals with type 2 diabetes, as well as associations of the GRIK3 (rs534131) and GRIA1 (rs2195450) genes with diabetic retinopathy." (PMID 40740189, 2025).
AIDS (1 paper, 2024). A syndrome resulting from the acquired deficiency of cellular immunity caused by the human immunodeficiency virus (HIV). "One observational clinical study suggests that overall NMDAR expression is reduced in the frontal cortex of individuals with AIDS and HAD, whereas we observe increased Grin1 and Grin2a transcript expression specifically in rat mPFC." (PMID 38514527, 2024).
channelopathies (1 paper, 2018). "Furthermore, both the gain- and loss-of-function phenotype can be observed in other channelopathies such as KCNA2, GRIN1, and DEAF1 gene mutations." (PMID 29545233, 2018).
congenital myopathy (1 paper, 2017). "Mice with mutations in Grin1 also show abnormal anxiety-like behaviors, a deficiency in fear memory, and a decreased startle amplitude, and mice with Cfl2 mutations display features of congenital myopathy." (PMID 28751711, 2017).
Dysphagia (1 paper, 2021). "The study of the GRIN1-DNV cohort showed a relative high prevalence of GI distress (5 out of 15), mostly associated with dysphagia, gastroesophageal reflux, and constipation." (PMID 34884460, 2021).
emotional instability (1 paper, 2016). "The emotional instability significantly differed in individuals carrying the GRIN1 (rs4880213) and GRIN2B (rs7301328) polymorphisms." (PMID 26819771, 2016).
focal epilepsies (1 paper, 2025). "For example, in the GluN cluster of patients with FCDII, we observed downregulation of GRIN1 and PRRT2, two genes causing monogenic forms of focal epilepsies, and upregulation of GLUL, pointing toward alterations of the glutamate signaling and neurotransmission in glutamatergic neurons." (PMID 40307383, 2025).
Glucose intolerance (1 paper, 2021). Glucose intolerance (GI) can be defined as dysglycemia that comprises both prediabetes and diabetes. "Furthermore, NMDAR loss (Grin1/GluN1 KO) was associated with impaired islet GSIS and glucose intolerance in some models." (PMID 33430405, 2021).
kidney cancer (1 paper, 2022). Primary or metastatic malignant neoplasm involving the kidney. "Our experimental results are consistent withthe literature showing GRIN1 underexpression in schizophrenic disorders as well as an increased risk of cervical,bladder, and kidney cancers and lymphoma during ASCL3 underexpression." (PMID 35774364, 2022).
lung carcinoma (1 paper, 2022). "Only the expression of GPR54 was associated with CD8+ T cell infiltration in lung cancer, although Grin1 (glutamate receptor), Ptger1 (prostaglandin E receptor 1), Hrh2 (histamine receptor), Ghsr (growth hormone secretagogue receptor), and Tacr1 (substance P receptor) were detected." (PMID 35224894, 2022).
lupus (1 paper, 2022). "Indeed, most Nr4a1-controlling genes (Grin1, Creb3l3, Mef2a, Mef2c, and Mef2d) were reduced in the lupus hippocampus, as revealed by sequencing assays." (PMID 35177587, 2022).
mood disorder (1 paper, 2021). A cognitive disorder a disturbance in which the person's mood is hypothesized to be the main underlying feature. "In contrast with the pathognomic presence of ID and language deficits, GRIN1-DNVs cohort showed a variable presence of mood disorders (e.g., irritability, aggressivity, hyperactivity; 8 out of 15 individuals), as well as sleep disorder (6 out of 15), in a variant-dependent manner." (PMID 34884460, 2021).